CTLA4 (cytotoxic T-lymphocyte associated protein 4)
Diseases named in the same sentence as CTLA4 in open-access papers (continued):
Sharing a sentence is not in itself a finding about the gene and the disease.
tumor (continued). "We observed that Fc-enhanced mouse anti-CTLA-4 antibodies (9D9 mouse IgG2a) eliminate tumor endothelial cells indiscriminately, including the beneficial MECA-79+ TA-HECs." (PMID 40460830, 2025). "The association between PIEZO1 and tumor microenvironment scores (Stromal, Immune, ESTIMATE) or immune checkpoint markers (CD274, CTLA4, LAG3, PDCD1, PDCD1LG2) were analyzed using the R language." (PMID 40977743, 2025). "The stiff subtype exhibited significantly increased tumor mutual burden and T cell follicle helper cell levels compared with the soft subtype, along with the expression of CTLA4, CD276, CD47, and TNFRSF25." (PMID 40277910, 2025). "The findings demonstrated that iron oxide NP-mediated PTT can promote CTLA-4 suppression of tumor development and specifically kill Tregs at the tumor locations." (PMID 40230883, 2025). "In contrast, both Fc-null and parental 9D9 increased Tregs in tumor-draining lymph nodes (TDLNs), confirming that peripheral expansion of Tregs is Fc-independent during anti-CTLA-4 therapy." (PMID 40460830, 2025). "Effective tumor cell killing is made possible by checkpoint inhibition, which targets molecules such as CTLA-4 and PD-1/programmed death-ligand 1 (PD-L1) to restore depleted T-cell function." (PMID 40230883, 2025). "In this study, we design a proof-of-concept treatment strategy: intratumor injection guided by CT scanning for delivery of PD-1 or PD-L1 inhibitor plus CTLA-4 inhibitor to initiate or reinitiate a better and safer anti-tumor immune system." (PMID 41459523, 2025). "Tumors can exploit this pathway by upregulating CTLA-4 expression or recruiting CTLA-4-expressing Tregs to suppress anti-tumor immunity." (PMID 40565041, 2025). "Hydrogel-encapsulated anti-CTLA-4 antibody has enhanced target delivery and anti-tumor effects in tumor-draining lymph nodes (TDLN) after the addition of hyaluronidase." (PMID 40646377, 2025). "In T cells, downregulation of AL031775.1 impairs antitumor immunity, upregulates immune checkpoint molecules LAG3, PD1, and CTLA4, and diminishes T-cell cytotoxic activity against tumor cells." (PMID 40066455, 2025). "Recent studies silencing both VISTA and CTLA‐4 have provided new avenues to enhance T‐cell anti‐tumor responses, potentially overcoming the issue of low immunotherapy response rates." (PMID 40356222, 2025). "Combining NBTXR3 with HDXRT, LDXRT, and anti-PD-1/anti-CTLA4 slowed tumor growth, reduced lung metastases, and improved survival, with some mice achieving complete tumor eradication." (PMID 41408568, 2025). "In the context of MIBC, the use of immunotherapy to target PD-1 and CTLA-4 checkpoints has shown promising results in counteracting tumor progression." (PMID 39857739, 2025). "ICT targets cytotoxic T lymphocyte antigen 4 (CTLA4) and PD-1/PD-L1, activating the body’s immune response to kill tumor cells." (PMID 40426972, 2025). "CTLA-4 regulates T cell activation in lymphoid tissues, while PD-1/PD-L1 interactions suppress T cell activity at the tumor site." (PMID 41373813, 2025). "Combination strategies using co-stimulatory receptor agonists are particularly promising in combination with other immunotherapies, such as checkpoint inhibitors (e.g., anti-PD-1, anti-CTLA-4), cytokine therapies, and tumor vaccines." (PMID 39857682, 2025). "Our present findings demonstrate that anti-CTLA-4 antibodies remodel tumor vasculature through Fc-dependent mechanisms." (PMID 40460830, 2025). "The activation of immune checkpoint pathways, such as Programmed Death-1 (PD-1)/Programmed Death- Ligand 1 (PD-L1) and Cytotoxic T-Lymphocyte Antigen 4 (CTLA-4), represents a crucial mechanism by which tumor cells evade immune surveillance." (PMID 40842533, 2025). "Significantly, blocking CTLA-4 with antibodies reverses these suppressive effects, restoring DC function, promoting T-cell responses, and directly inhibiting tumor cell viability and proliferation." (PMID 40281554, 2025).
tumor (continued). "In the tumor microenvironment, the high expression of CTLA-4 facilitates the evasion of tumor cells from the immune system’s attack and maintains an immunosuppressive state." (PMID 41415276, 2025). "Accordingly, tumors with high p62 and low immunoscore would be expected to exhibit reduced PD1 and CTLA4 expression, simply due to fewer infiltrating T cells within the tumor microenvironment." (PMID 41291343, 2025). "In colorectal carcinoma, inhibitory checkpoint molecules such as PD1, Tim3 and CTLA4 are transferred from regulatory T cells to tumor cells, enhancing immune suppression." (PMID 41181711, 2025). "This review will discuss the pathophysiology of NMIBC, highlighting the major factors influencing tumor progression within its microenvironment, the role of PD-L1 and CTLA-4 in UBC, and current clinical trials targeting these checkpoints." (PMID 40227644, 2025). "Immune checkpoint blockade is a key immunotherapy strategy targeting molecules like CTLA-4, PD-1, and PD-L1, which are involved in suppressing immune responses and allowing tumor cells to evade detection." (PMID 41373813, 2025). "In the pharmacoprevention context, immune checkpoint molecules such as CTLA-4, PD-1, and PD-L1 are emerging targets to restore immune surveillance and intercept tumor development." (PMID 41300964, 2025). "CTLA-4 inhibitors relieve this inhibitory signal, activating specific effector T cells to induce or enhance anti-tumor immune responses." (PMID 40242773, 2025). "When combined with immune checkpoint inhibitors (anti–PD-1 and anti–CTLA-4), oral reovirus administration achieves complete tumor regression and establishes durable immune memory, highlighting its promise as a non-invasive immunotherapy." (PMID 40507337, 2025). "Further, we investigate the potential of the soluble isoform of CTLA-4, sCTLA-4, as a confounding factor for current therapies, but also as a therapeutic for delivering antigen-specific anti-tumour immunity." (PMID 40265076, 2025). "Macrophages in the TME recognize and phagocytose Tregs with high CTLA-4 expression, whereas CD8 + effector T cells, with low CTLA-4 expression, remain unaffected, further enhancing the efficiency of the anti-tumor immune response." (PMID 40012016, 2025). "Malignant cells frequently upregulate checkpoint molecules, like PD-1 or CTLA-4, to inhibit and evade the T-cell mediated immune response directed against the tumor." (PMID 40102596, 2025). "A significant positive correlation between PD‐1 and CTLA‐4 expression on the whole tumour area was observed (Spearman's rank correlation coefficient = 0.56, p = 0.025)." (PMID 39789732, 2025). "Although the combination of anti-PD-1/PD-L1 and anti-CTLA-4 agents has demonstrated superior efficacy over monotherapy in multiple tumor types, its clinical benefits in specific malignancies such as HNSCC require further precise delineation." (PMID 41425253, 2025). "Co-inhibition of PD-1 and CTLA-4 induces a synergistic anti-tumor response by reshaping the tumor immune microenvironment into a more immunogenic phenotype." (PMID 40433373, 2025). "AK104 facilitates the independent endocytosis of PD-1 or CTLA-4, demonstrating good antigenic differentiation and high retention in the tumor tissue." (PMID 40075727, 2025). "Subsequently, at the Post‐NT state, these cells displayed increased synthesis of T‐cell suppressive factors such as Tnfaip3, Ccl5 and Ctla4,89, 90, 91 coinciding with tumour emergence." (PMID 40887856, 2025). "Current clinical approaches utilizing Tregs include immune checkpoint inhibitors like CTLA4 inhibitors, which boost anti-tumor immunity while maintaining Treg–mediated tissue balance." (PMID 39857718, 2025). "RP2 retains the design features of RP1, with the added expression of an anti-CTLA-4 antibody-like molecule designed to be expressed within tumors and secreted into the local tumor microenvironment for local CTLA-4 blockade on T cells within tumors." (PMID 41148835, 2025).
tumor (continued). "This review will examine how antibodies specific for CTLA-4 enhance anti-tumour immunity and highlight a largely unrecognized novel function, masked by current anti-CTLA-4 antibodies." (PMID 40265076, 2025). "Here, we investigate the mechanisms by which anti-CTLA-4 antibodies modulate TA-HEVs and T cell-dependent antitumor immunity in preclinical mouse tumor models." (PMID 40460830, 2025). "Variable responses to anti–CTLA-4 antibody treatment alone were observed; tumor growth was controlled in 50% of the MC38 tumor–bearing mice with the remaining 50% of mice having tumor growth comparable to control." (PMID 39881590, 2025). "The combination of MAP and anti‐CTLA‐4 therapy effectively enhanced the infiltration of NK and T cells and promoted tumor cell apoptosis." (PMID 39499771, 2025). "As a result, monotherapies targeting PD-1 or CTLA-4 often result only in modest anti-tumor activity." (PMID 41228234, 2025). "In conclusion, our study demonstrated mRNA expression of PD‐L1, PD‐1 and CTLA‐4 by both neoplastic and immune cells in canine OMs, supporting their role in immunosuppression and in promoting tumour progression." (PMID 39789732, 2025). "CTLA4 exhibited cytoplasmic immunostaining in both adjacent normal tissues and tumor cells, with particularly strong expression observed in T1‐stage tumor specimens." (PMID 40099956, 2025). "HTE tumours show upregulation of members of multiple immune-related pathways, including PD-1, PD-L1, CTLA4, FOXP3, and IDO1, suggesting the utility of combination immunotherapy." (PMID 40849356, 2025). "Aptamers targeting immune checkpoint molecules, such as PD-1 or CTLA-4, can enhance anti-tumor immunity by blocking inhibitory signals that suppress T cell activation." (PMID 40870970, 2025). "Despite Teffs binding to tumour cells, immunological checkpoints like PD‐L1 and CTLA4 aid tumour cells." (PMID 40916076, 2025). "The unique design of Cadonilimab lies in its tetravalent structure, which enables multivalent binding to T cells co-expressing PD-1 and CTLA-4 within the tumor micro-environment." (PMID 41561746, 2025). "ICIs reverse T-cell exhaustion, activate local and systemic immune responses, and break the tumor immune escape mechanism by blocking the PD-1/PD-L1 or CTLA-4 pathways." (PMID 40308503, 2025). "ICT targets CTLA4 and PD-1/PD-L1, which are utilized by tumor cells to suppress anti-cancer immune responses." (PMID 40426972, 2025). "Given the synergistic effects of cisplatin and CTLA-4 inhibitors, this combination therapy can improve anti-tumor immune responses and overcome drug resistance, and warrants more preclinical and clinical studies." (PMID 39757995, 2025). "In a limited cohort of 10 patients treated with relma-cel, the CR group demonstrated significantly higher relative mRNA expression of LAG3 and CTLA4 in pre-treatment tumor biopsies." (PMID 39858099, 2025). "mRNA-based vaccines targeting MUC1 aim to induce tumor-specific immune responses, while siRNA-mediated silencing of CTLA-4 offers a more targeted approach to immune modulation." (PMID 40943370, 2025). "Tumor cells evade immune detection by upregulating immune checkpoint molecules such as CTLA-4 and PD-1 on T lymphocytes." (PMID 40070819, 2025). "The transplantation of Bacteroides fragilis into patients has been shown to enhance tumor responsiveness to CTLA‐4 inhibitors." (PMID 40672434, 2025). "In this study, we demonstrated the in situ mRNA expression of PD‐L1, PD‐1 and CTLA‐4 in both tumour cells and immune cells of the TME in canine OM." (PMID 39789732, 2025). "Another study demonstrated that combining entinostat with anti-PD-1, anti-CTLA-4, or both significantly improved tumor-free survival in HER2/neu transgenic breast cancer and Panc02 metastatic pancreatic cancer mouse models." (PMID 41024300, 2025).
tumor (continued). "CTLA‐4 serves as a ligand functioning as an immunomodulator in the interplay between tumor cells and immune cells; it is notably expressed in activated T cells to inhibit subsequent activation." (PMID 40551477, 2025). "Several groups, however, have used murine models to evaluate the mechanism of anti-CTLA-4 activity, providing evidence that the killing of immune cells is required for anti-tumour activity to occur." (PMID 40265076, 2025). "We first assessed Treg cell expression of the activation markers PD-1, Tim-3, and CTLA-4 in the TdLN, tumor-adjacent skin, early tumors, and late tumors." (PMID 41279375, 2025). "For example, inhibiting LDHA or lactate transporters in combination with anti-CTLA-4 therapy leads to increased infiltration of cytotoxic T cells and reduced regulatory T cells, thereby improving anti-tumor immune responses." (PMID 40535811, 2025). "Lactate acidifies the tumor cell microenvironment, which inhibits the anti-tumor immune response, influences CTLA-4 production via the EPAC1 signaling pathway, and strengthens its capacity to prevent effector T cell activation." (PMID 40917751, 2025). "Lorigerlimab (MGD019) is a bispecific Fc-bearing (IgG4) (dual-affinity re-targeting molecule) DART molecule designed to enhance CTLA-4 blockade on tumor infiltrating lymphocytes, while maintaining maximal PD-1 blockade on PD-1 expressing cells." (PMID 39833954, 2025). "Alternatively, the primary site of T cell regulation by PD-1 has been reported to occur in a localized manner in the peripheral tissues, like the tumor, whereas CTLA-4 predominantly was shown to exert its function within the lymphoid organs." (PMID 40335925, 2025). "Among them, MDSCs are regulatory immune cells associated with chronic inflammation and tumor sites, and inhibit CD8 + T-cell function through the expression of PD-1 and CTLA-4." (PMID 39141277, 2025). "Immune checkpoint blockade therapies, using antibodies against PD-1 and CTLA-4, have been shown to facilitate the continuous recruitment of T cells into tumors, contributing to significant anti-tumor effects." (PMID 41331976, 2025). "A major challenge in CAR-T cell therapy for solid tumors is T cell exhaustion following tumor infiltration, characterized by upregulation of inhibitory receptors (e.g., PD-1, CTLA-4, LAG-3, TIM-3) and diminished proliferative capacity and antitumor activity." (PMID 40755764, 2025). "The foundation of ICIs began in the early 1980s with James Allison’s discovery of tumor antigens and the T-cell receptor, followed by the identification of CTLA-4 in 1987." (PMID 40867265, 2025). "When combined with CTLA-4 inhibitors, it significantly enhances the anti-tumor efficacy of immune checkpoint blockade therapies." (PMID 41479917, 2025). "In the current study, we found that patients with high levels of the immune-related gene CTLA4 in tumor had an excellent prognosis, likely because the immune system aids in fighting the cancer." (PMID 40523912, 2025). "PD-L1 was positive in both tumor cells and in tumor-infiltrating cells, while CTLA-4, PD-1, PD-L1, TIM-3, TIGIT, and VISTA were mainly observed in tumor-infiltrating cells." (PMID 40565313, 2025). "CTLA-4 is observed in granular deposits in the cytoplasm and membrane of infiltrating lymphocytes and tumor cells." (PMID 40565313, 2025). "Building upon our earlier findings, we selected CTLA-4 blockade as the combination therapy for SFN in CT26 tumor model." (PMID 39961271, 2025). "Checkpoint inhibitors targeting CTLA-4 or PD-1/PD-L1 have revolutionized oncology, yet heterogeneous responses underscore the complexity of tumor–immune interactions." (PMID 41339918, 2025). "When controlling for tumor size, CTLA4 expression remained significant in SCAN-B (HR 0.63, P = 0.011), but not in METABRIC (HR 0.72, P = 0.09)." (PMID 40523912, 2025).
tumor (continued). "Immune checkpoint inhibitors (ICIs), such as PD-1 and CTLA-4 inhibitors, restore T cell function by alleviating the immunosuppressive effects of the tumor microenvironment, enabling T cells to effectively attack tumor cells." (PMID 40070819, 2025). "CTLA4 is not only expressed on T cells, but also on B lymphocytes, natural killer (NK) cells, monocytes, dendritic cells, and even certain tumor cells." (PMID 40005446, 2025). "With this presentation, DCs can enhance T-cell activation, which synergizes with CTLA-4 blockade to promote tumor elimination." (PMID 41228220, 2025). "In murine models of HCC, simultaneous blockade of PD-1 and CTLA-4 led to significantly enhanced tumor regression compared to either therapy alone." (PMID 41013723, 2025). "While PD-1 inhibitors target peripheral T cell activation, especially in the tumor context, CTLA-4 antagonists affect T cell priming." (PMID 40777043, 2025). "Anti-CTLA-4 blockade enables T-cell tumour infiltration, enhancing immune responses, as seen in murine breast cancer models." (PMID 40361472, 2025). "CTLA-4 is primarily expressed in Tregs and functionally exhausted T cells, and is also detectable on the surface of tumor-infiltrating NK cells, where its expression inhibits myeloid dendritic cell (mDC)-induced IFN-γ production." (PMID 40463500, 2025). "CTLA-4 upregulation during T cell activation suppresses T cell activity, particularly on tumor-infiltrating regulatory T cells (Tregs) and exhausted effector T cells (Teffs)." (PMID 40070819, 2025). "Patients receiving anti-CTLA-4 therapy sometimes exhibit a delayed response for some weeks or months before anti-tumour immunity becomes apparent." (PMID 40265076, 2025). "By targeting PD-1, PD-L1, or CTLA-4 pathways, ICIs restore cytotoxic T-cell activity and induce durable tumor responses in a subset of patients with advanced disease." (PMID 40647391, 2025). "CTLA-4 inhibitors, such as ipilimumab, enhance T-cell activity and promote T-cell proliferation and cytokine secretion by blocking the binding of CTLA-4 to B7 molecules, thereby activating the immune system’s attack on tumor cells." (PMID 41346595, 2025). "Research demonstrates that combining propranolol with anti-CTLA4 therapy significantly improves treatment outcomes, reduces tumor growth rates, and increases overall survival." (PMID 40860838, 2025). "They showed that the dMMR subset of tumours selectively upregulated multiple checkpoint proteins, including PD-L1, PD-1, CTLA-4, IDO, and LAG3." (PMID 40647497, 2025). "Immune checkpoint inhibitors (ICIs) such as anti-PD-1/PD-L1 and anti-CTLA-4 antibodies have obtained regulatory approvals across various tumour types and indications." (PMID 40518502, 2025). "One previous study demonstrated that Bacteroides fragilis can trigger dendritic cell maturation and stimulate IL-12-dependent Th1 cell infiltration, thereby enhancing the anti-tumor effects of anti-CTLA-4 therapy." (PMID 41304278, 2025). "CTLA-4 immune checkpoint inhibition and IFNα LV infusion boost tumor-reactive T cells, leading to a complete response in most animals." (PMID 40422244, 2025). "Immune checkpoint inhibitors, such as anti-CTLA-4 and anti-PD-1/anti-PD-L1, are frequently utilized in tumor immunotherapy." (PMID 40088376, 2025). "CTLA-4 is a negative regulator of T cell activation in the context of antitumor immunity; in preclinical models, monoclonal antibody-mediated inhibition of CTLA-4 leads to tumor regression and long-lasting antitumor immunity." (PMID 40861696, 2025). "This subtype is associated with enhanced local anti-tumor immunity, where infiltrating CD8+ T cells show increased cytolytic activity, accompanied by increased expression of co-regulatory molecules (CTLA-4, PD-L1, PD-L2, and IDO-1)." (PMID 40264765, 2025).